PGRMC1 (progesterone receptor membrane component 1)
Description:
Component of a progesterone-binding protein complex. Binds progesterone. Has many reported cellular functions (heme homeostasis, interaction with CYPs). Required for the maintenance of uterine histoarchitecture and normal female reproductive lifespan (By similarity). Intracellular heme chaperone. Regulates heme synthesis via interactions with FECH and acts as a heme donor for at least some hemoproteins.
Synonyms: mPR; HPR6.6; Dap1; IZA
Tractability: Small molecule: a structure with a bound ligand is known. Antibody: UniProt places it where antibodies can reach, with high confidence; its Gene Ontology location is reachable by antibodies, with high confidence; UniProt predicts a signal peptide or a membrane-spanning region. PROTAC: ubiquitination databases record sites on it; its protein half-life has been measured; a small molecule that binds it is known.
Gene: Protein-coding gene on chromosome X (119,236,244 to 119,244,468, forward strand). Ensembl gene ENSG00000101856.
Subcellular location: Microsome membrane; Smooth endoplasmic reticulum membrane; Mitochondrion outer membrane; Secreted
Subcellular location (Human Protein Atlas): Endoplasmic reticulum; Mid piece; Nucleoli; Principal piece; Predicted to be secreted
Pathways (Reactome):
Immune System: Neutrophil degranulation
Gene Ontology:
Molecular function: heme binding; protein binding; protein homodimerization activity; amyloid-beta binding; steroid binding
Biological process: heme biosynthetic process; positive regulation of lipoprotein transport; positive regulation of protein localization to plasma membrane; associative learning; axon guidance; memory; modification of synaptic structure; negative regulation of synapse organization
Cellular component: extracellular region; membrane; cell body; endoplasmic reticulum; mitochondrial outer membrane; neuron projection; neuronal cell body; plasma membrane; smooth endoplasmic reticulum membrane; specific granule membrane; synapse
Homologues: Orthologues: chimpanzee PGRMC1 (100% identical), macaque PGRMC1 (99% identical), pig PGRMC1 (96% identical), mouse Pgrmc1 (95% identical), dog PGRMC1 (94% identical), rabbit PGRMC1 (94% identical), guinea pig PGRMC1 (93% identical), rat Pgrmc1 (93% identical), tropical clawed frog pgrmc1 (67% identical), zebrafish pgrmc1 (62% identical), Drosophila melanogaster MSBP (50% identical), Caenorhabditis elegans vem-1 (36% identical), and 1 more. Paralogues in human: PGRMC2 (51% identical), CYB5D2 (28% identical), VMP1 (17% identical).
Diseases named in the same sentence as PGRMC1 in open-access papers:
PGRMC1 is named in the same sentence as 129 diseases in open-access papers, as found by Europe PMC text mining. Sharing a sentence is not in itself a finding about the gene and the disease. The quoted sentences say what the papers report.
breast carcinoma (52 papers, 2008 to 2025). "PGRMC1 exhibited a robust positive association with signature-derived proliferation scores across all breast cancers (r = 0.268; P = 6.5 × 10−17)." (PMID 39804138, 2025). "TCGA data containing 1,019 breast cancers were analyzed in an exploratory fashion to evaluate expression patterns associated with PGRMC1." (PMID 39804138, 2025). "PGRMC1 expression has been shown to modulate ovarian cancer's sensitivity to chemotherapy and is linked to alpha estrogen receptors and hypoxia in breast cancer." (PMID 39502961, 2024). "In previous studies, we demonstrated that PGRMC1 is partially required for progestin signaling in MCF7 cells and therefore suggested a potential role of PGRMC1 in the increased breast cancer risk upon progestin-based HT." (PMID 34830790, 2021). "Our study showed that Pgrmc1 regulates the metastasis and migration of breast cancer cells, although the underlying mechanism of this phenomenon was not thoroughly delineated." (PMID 33832499, 2021). "Our data underline the contribution of PGRMC1 to especially hormone receptor positive breast cancer pathogenesis and demonstrate the need for further studies to understand its role in cancer." (PMID 34830790, 2021). "Our team has been focusing on the association between PGRMC1 and breast cancer during the past decade." (PMID 34746100, 2021). "In previous studies, we reported that progesterone receptor membrane component 1 (PGRMC1) is implicated in progestin signaling and possibly associated with increased breast cancer risk upon combined hormone replacement therapy." (PMID 34830790, 2021). "Our data underline the contribution of PGRMC1 to especially hormone receptor positive breast cancer pathogenesis and demonstrate the urgent need for further studies." (PMID 34830790, 2021). "As part of our investigations, we observed that both chemical inhibition and silencing of PGRMC1 reduce cell proliferation, induce apoptosis, cause cell-cycle arrest and inhibit invasion and migration of breast cancer cells." (PMID 32704174, 2020). "Our data underline the contribution of PGRMC1 to especially hormone receptor-positive breast cancer pathogenesis in vitro and in vivo and suggest its potential as a target for anti-cancer therapy." (PMID 32660617, 2020). "Many reports have implicated that the PGRMC1 expressed predominantly in human liver, ovary, and kidney tissue, and is known to be over-expressed in various types of cancers, including breast cancer, head and neck cancer, ovarian cancer, and lung cancer." (PMID 31970154, 2019). "Recent studies have implicated that PGRMC1 plays important roles in multiple cancers, including breast cancer, ovarian cancer and lung cancer." (PMID 28107520, 2017). "PGRMC1 protein affects the response to oxidative damage in the MCF-7 breast cancer cell line, influencing their susceptibility to oxidative cell death." (PMID 18922159, 2008). "Stable expression of PGRMC1 (Hpr6.6) enhances the susceptibility of MCF-7 breast cancer cells to lethality caused by H2O2 exposure." (PMID 18922159, 2008). "Although the mechanisms underlying the association of PGRMC1 with proliferation are unknown, potential effector pathways associated with PGRMC1 expression in breast cancer provide a possible explanation." (PMID 39804138, 2025). "As the expression of PGRMC1 and TK1 are associated with proliferation in human breast cancers, we next asked whether PGRMC1 expression was associated with the expression of TK1." (PMID 39804138, 2025). "The expression of a heme-binding defective PGRMC1 mutant and the resulting increased susceptibility of breast cancer cells to chemotherapeutic agents evidences a role for holo-PGRMC1 in regulating susceptibility to DNA damaging agents, similarly to its yeast homolog Dap1." (PMID 38804287, 2024). "Moreover, elevated PGRMC1 expression in breast cancer has been linked to more advanced stages and a poor prognosis." (PMID 37894441, 2023).
breast carcinoma (continued). "Pgrmc1 is also known to be highly expressed in various types of cancers and associated with the survival rate of patients with head and neck cancer, lung and ovarian cancers, and breast cancer." (PMID 34069911, 2021). "Indeed, PGRMC1 can promote tumorigenesis, and its expression is associated with a malignant breast cancer phenotype." (PMID 34831222, 2021). "Importantly, Pgrmc1 is associated with the expression of estrogen receptor alpha and can be used for predicting the prognosis of breast cancer." (PMID 33832499, 2021). "The aim of the present study was to investigate the impact of PGRMC1 on lipid metabolism, lipid raft formation, and its contribution to breast cancer progression and cancer-associated signaling pathways in hormone receptor-positive (MCF7) and hormone receptor-negative (MDA-MB-231) cells." (PMID 32660617, 2020). "Moreover, a strong association between PGRMC1 over-expression and worse overall survival of breast cancer, acute myelocytic leukemia, and sarcoma patients was also observed." (PMID 31970154, 2019). "The characterization of the PGRMC1 phosphorylation state and associated function requires further investigation and is important for a better understanding of the involvement of PGRMC1 in increased breast cancer risk in progestin-based hormone therapy." (PMID 29069804, 2017). "PGRMC1 may also be associated with breast cancer chemotherapeutic resistance in vitro." (PMID 39804138, 2025). "Furthermore, considering that Pgrmc1 expression is associated with ERa expression, suppression of Pgrmc1 has been considered as a potential therapeutic approach against the progression of breast cancer." (PMID 33832499, 2021). "In breast cancer, PGRMC1 is markedly overexpressed and has been identified as a novel biomarker for characterizing estrogen receptor status and tissue hypoxia." (PMID 41153737, 2025). "Our data demonstrate that differential expression of PGRMC1 in human breast cancer is a function of cell proliferation, as well as breast cancer receptor and molecular subtypes, and further reveal an association between PGRMC1 and cell-cycle markers." (PMID 39804138, 2025). "In breast cancer cells, PGRMC1 interacts with estrogen receptor α (ERα), activating the ERα signaling pathway and thereby promoting cancer cell proliferation." (PMID 41153737, 2025). "PGRMC1 facilitates triple-negative breast cancer tumor growth in vivo, and in an ER+ human breast cancer cell line that overexpresses PGRMC1, medroxyprogesterone acetate and norethisterone treatment significantly increased proliferation." (PMID 39804138, 2025). "Our results are in line with a previous observation that inhibition and silencing of PGRMC1 in breast cancer decreased cell proliferation, migration, and invasiveness, as well as inducing cell-cycle arrest and apoptosis of cancer cells." (PMID 39464509, 2024). "Progesterone receptor membrane component 1 (PGRMC1) is expressed in various tissues, including the liver, uterus, ovary, heart, and mammary gland, and in breast cancer." (PMID 38397828, 2024). "We have recently demonstrated in breast cancer cells, that progestin-activated PGRMC1 interacts with PHB1/PHB2 resulting in enhanced ERα-dependent transcription and cell proliferation." (PMID 38308254, 2024). "In order to examine the effect of PGRMC1 on aromatase (CYP19A1) activity in breast cancer, MCF-7 (hormone-responsive) cells were engineered for expression of an epitope-tagged aromatase and PGRMC1 was knocked down." (PMID 38804287, 2024).
breast carcinoma (continued). "Pgrmc1 expression is induced by dioxin during rat liver tumorigenesis, as well as in the human breast cancer cell line, MCF-7, and in women chronically exposed to industrial chemical pollutants." (PMID 38804287, 2024). "PGRMC1 was perinuclearly localized in breast cancer cells, while in the nuclei or concentrated at or near the plasma membrane of granulosa cells." (PMID 38804287, 2024). "Traditionally, PGRMC1 has been studied for its overexpression and sensitivity to progesterone in ovarian and breast cancers." (PMID 39502961, 2024). "Compared to other breast cancer subtypes, progesterone receptor membrane component-1 (PGRMC1) was the highest expressed in TNBC." (PMID 37928550, 2023). "One study showed that ectopically expressed PGRMC1 in an nPR(−) breast cancer cell line (MDA-MB-231) can induce upregulation of both PGRMC1 and mPRα proteins on the cell membrane while also increasing PRG levels bound to mPRα in cell membranes." (PMID 36984647, 2023). "The involvement of FDFT1 in breast cancer progression through interaction with PGRMC1, a key protein in lipid metabolism, is considered to be a potential basis for breast cancer treatment." (PMID 35976950, 2022). "In our previous studies, progesterone receptor membrane component 1 (PGRMC1) was shown to play a role in progestins’ elicitation of enhanced proliferation of breast cancer cells." (PMID 34830790, 2021). "In vitro analysis, PGRMC1 also regulated the migration of both luminal A and triple-negative subtypes of breast cancer cells, especially in a steroid-starved condition." (PMID 33832499, 2021). "One example is the role of Pgrmc1 in breast cancer, as Pgrmc1 has been recently identified to play important roles in the survival duration and metastasis of breast cancers in a murine PyMT model." (PMID 34069911, 2021). "Bioinformatic approaches were performed to analyzed the expression of PGRMC1 among different subtypes of breast cancers using RNA-seq data from the TCGA, METABRIC and GEO databases." (PMID 34746100, 2021). "In the present study, we used transgenic MMTV-PyMT mice that spontaneously develop breast cancer and deleted the Pgrmc1 gene." (PMID 33832499, 2021). "Pgrmc1 KO mice with breast cancer had a prolonged survival, which was accompanied by a low degree of lung metastasis." (PMID 33832499, 2021). "In previous studies, we provided evidence that PGRMC1 is involved in the mode of action of progestins on breast cancer cells." (PMID 34830790, 2021). "Increased relative gene expression and copy number variation of CCND1 and YWHAZ was observed in MDA-MB-468 breast cancer cells and silencing PGRMC1 reduced the expression of these genes." (PMID 34350123, 2021). "Here we describe a potential mechanism by which PGRMC1 contributes to breast cancer progression via interaction with prohibitins, inhibiting their function as transcriptional repressors." (PMID 34830790, 2021). "Regarding hormone-sensitive cancers, PGRMC1 has been shown to regulate some breast cancer hallmarks." (PMID 34831222, 2021). "Considering the previous findings on the association between ER and Pgrmc1, the slight decrease in the development of breast cancer in the Pgrmc1 KO mice was unexpected." (PMID 33832499, 2021). "Once we identified the altered pathways following PGRMC1 signal disruption by AG-205 treatment we wanted to identify if the genes that are directly involved within these pathways are observed in breast cancer patient samples." (PMID 34350123, 2021). "On the other hand, the membrane receptor PGRMC1 can block the proliferative cascade in breast cancer cells." (PMID 34683909, 2021). "PGRMC1 can promote breast cancer development by increasing survival and growth of tumor cells and inducing neovascularization in tumor tissue through VEGF activation." (PMID 34831222, 2021).
breast carcinoma (continued). "For example, medroxyprogesterone acetate, norethisterone, and dienogest, but not nomegestrol acetate, induce proliferation in MCF7 and T47D breast cancer cells by a mechanism that depends on phosphorylation of a casein kinase 2 domain within PGRMC1." (PMID 34885064, 2021). "This would be extremely instructive since a link between PGRMC1, estradiol/estradiol receptor and breast cancer progression was evidenced in other reports that relied on downregulation or overexpression of PGRMC1, and are therefore not challenged by our study." (PMID 34680104, 2021). "We report that PGRMC1 overexpression resulted in increased proliferation of hormone receptor positive breast cancer cell lines upon treatment with a subgroup of progestins including norethisterone and dydrogesterone that promote PGRMC1-phosphorylation on S181." (PMID 34830790, 2021). "As metastatic breast cancer has a high mortality rate, Pgrmc1 should be highlighted as a possible target for regulating tumor metastasis and increasing the survival expectancy of patients with breast cancer." (PMID 33832499, 2021). "Several studies have investigated the relevance between PGRMC1 and migration in various types of cancers; accordingly, we focused on how to detect the breast cancer cells undergoing EMT in culture systems." (PMID 33832499, 2021). "For this purpose, potential PGRMC1-interaction partners in breast cancer cells were evaluated with norethisterone (acetate) (NET) treatment." (PMID 34830790, 2021). "For survival analysis, GEPIA2 was used, which revealed that low expression of PGRMC1 in patients with breast cancer showed better overall survival (p = 0.027)." (PMID 34746100, 2021). "This is in line with the reported association between PGRMC1 and ER levels, the observed PGRMC1-mediated ERα activation and the increased breast cancer cell proliferation correlated with PGRMC1-ERα crosstalk recently reported." (PMID 34831222, 2021). "As Pgrmc1 is involved in estrogen synthesis, a recent study showed that a high level of Pgrmc1 promotes the development of breast cancer in a xenograft model." (PMID 33832499, 2021). "Various studies have demonstrated that elevated PGRMC1 expression promotes a more aggressive phenotype of breast cancer and participates in its carcinogenesis." (PMID 34830790, 2021). "In a previous study, we investigated PGRMC1 phosphorylation in MCF7 breast cancer cells after treatment with NET and identified S181 to be phosphorylated." (PMID 34830790, 2021). "Examples of this were σ1 expression in ovarian and breast cancer, PGRMC1 expression in lung and breast cancer, and σ2/TMEM97 in melanoma and breast cancer cell lines." (PMID 33466391, 2021). "The interaction partners detected in the present study will be an important starting point to further investigate the PGRMC1 signaling cascade in HR positive breast cancer." (PMID 34830790, 2021). "Since PHB1 and PHB2 were reported to regulate ERα signaling, which is a central oncogenic pathway in luminal breast cancer, we focused on the implication of PGRMC1 in the ERα signaling network and its possible involvement in breast cancer promotion." (PMID 34830790, 2021). "In the present study, we identified PGRMC1 as a factor that inhibits PHBs’ action as ERα co-regulators in the presence of certain progestins in our luminal breast cancer cell model." (PMID 34830790, 2021). "As already shown in previous studies, PGRMC1 represents a potential integration point and transmitter of progestin signals responsible for the growth and proliferation of breast cancer cells." (PMID 34830790, 2021). "This is consistent with a previous study that observed the progression of mammary tumors by PGRMC1 in triple-negative breast cancer." (PMID 33832499, 2021). "As a part of the present study, we determined that PGRMC1 specifically promotes breast cancer growth by activating the PI3K/AKT/mTOR and EGFR signalling pathway." (PMID 32704174, 2020).